NOTCH4 (notch receptor 4)
Diseases named in the same sentence as NOTCH4 in open-access papers (continued):
Sharing a sentence is not in itself a finding about the gene and the disease.
tumor (continued). "Given the complex dynamics in tumor-host interaction and tumor microenvironment, we cannot rule out the possibility that vascular Notch4 (and other Notch pathway proteins) may regulate tumor onset by mechanisms that are independent of vessel perfusion." (PMID 23601498, 2013). "However, in our studies, we did not observe Notch4 staining in either human or murine tumor cells, but rather observed Notch4 upregulation in the tumor vasculature." (PMID 23601498, 2013). "Indeed, the aberrant activity of Notch4 signaling has been described in CSC-like cells isolated from cancer cell lines and patients’ primary samples, and its selective inhibition by shRNA significantly affected the mammosphere formation and tumor initiation capabilities." (PMID 34680255, 2021). "Finally, since Notch4 has been reported to play a role in TNBC and is expressed in a population of tumor-initiating stem cells, we demonstrated that Notch inhibition might be an effective strategy for the treatment of BC, at least in an animal model that resembles human TNBC." (PMID 26059540, 2015). "The int-CAs showed higher expression of IR transcripts of NOTCH1 and NOTCH3 compared to the other tumor types but did not have the IR transcripts of NOTCH2 and NOTCH4 (p < 0.05)." (PMID 39101773, 2024). "In 370 HCC samples, the expression levels of Notch 1, Notch 2, Notch 3, Notch 4, DLL4, JAG1, and JAG2 were markedly greater in tumor samples compared to surrounding non-tumorous tissue." (PMID 38816668, 2024). "Tumor tissue in RT-R-MDA-MB-231-injected mice showed significant increases in the expression of CD44, Notch-4, and Oct3/4, but not ALDH1 in the present study." (PMID 33126606, 2020). "Compared with nontumor normal tissues, downregulation of Notch1 and Notch4 was observed in HCC tissues, while Notch2 expression was not significantly different between tumor and normal tissues." (PMID 28568708, 2017). "Having previously reported that Notch3 activation appeared to be associated with more aggressive disease, we have now examined components of this pathway (Notch1, Notch3, Notch4, HES-1, HEY-1) in more detail in resectable (n = 42) and non-resectable (n = 50) tumours compared to uninvolved pancreas." (PMID 23226563, 2012).
cancer (83 papers, 2004 to 2026). A tumor composed of atypical neoplastic, often pleomorphic cells that invade other tissues. "It has been observed that both the overexpression and mutations of the Notch4 gene are related to cancer." (PMID 38790158, 2024). "A great number of studies have addressed the role of Notch4 in cancer, particularly the molecular mechanisms associated with it." (PMID 37108670, 2023). "After adjusting for cancer type, NOTCH4 status was an independent prognostic factor associated with OS." (PMID 34284787, 2021). "NOTCH homolog-4 (NOTCH4) is frequently mutated in several cancer types, but its role in immunotherapy is still unclear." (PMID 34284787, 2021). "High Notch activity has been implicated in cancer pathogenesis and Notch 4 is specifically active within breast CSCs." (PMID 30975104, 2019). "Other Int genes, such as Int-2 and 4 (Fgf3, 4), and Int-3 (Notch4), encode mitogens and regulators of development that are also misactivated in many cancers." (PMID 17895999, 2007). "In HER2-positive luminal B cancer, overexpression of NOTCH4 was linked with worse OS." (PMID 41463075, 2025). "Similar to uLMS, NOTCH3 and NOTCH4 have been implicated in various cancers." (PMID 38927890, 2024). "It has been reported that NOTCH4 is implicated in cancer progression." (PMID 35136410, 2022). "Furthermore, Notch4 signaling, a key hallmark of cancer stem cells, is inhibited by 433‐3β." (PMID 40007440, 2025). "The level of APH1A, CTBP1, HEY1, HEY2, JAG2, NOTCH4 was significantly higher in cancer samples compared to the control group, while the concentration of DTX1 TLE2, TLE4 was below the detection threshold." (PMID 41463075, 2025). "DLL4 and NOTCH4 have been investigated for their roles in promoting metastasis and cancer stem cell activities, and their downregulation has been linked to a reduced metastatic burden and the inhibition of cancer stem cells." (PMID 38612588, 2024). "Both expression and DEG enrichment of JAG1, DLL1, and NOTCH4 significantly increased after anti-cancer therapy in BIC." (PMID 39074091, 2024). "NOTCH4, one of four transmembrane receptors in the NOTCH family, is frequently mutated in several cancer types." (PMID 36769068, 2023). "In this cancer, upregulation of Notch4 expression promotes metastasis through the regulation of Twist1 expression, which indicates a poor prognosis." (PMID 37108670, 2023). "The majority of studies have suggested that Notch4 expression is upregulated during the development of cancer." (PMID 37108670, 2023). "The varied functions of Notch4 signalling in cancer, as well as the possible outcomes and clinical utility of applying multiple Notch4-targeting treatment techniques, are likely to be further clarified in studies." (PMID 37108670, 2023). "In cancer, NOTCH4 activity is ambiguous, being a favorable marker in some cancers and associated with poor prognosis in others." (PMID 37509254, 2023). "Probably the poor clinical outcome of cancer patients with high expression of Notch4 is associated with its role in the mechanism of EMT, which is a very significant molecular event leading to cancer metastasis." (PMID 37108670, 2023). "Abnormal Notch4 signaling transduction can regulate multiple cellular behaviors to initiate cancer occurrence and progression." (PMID 35945960, 2022). "NOTCH homolog-4 (NOTCH4) has been correlated with a better response in several carcinomas including BUC." (PMID 36148227, 2022). "Univariate Cox regression analysis of PFS revealed that NOTCH4 status and cancer type had prognostic value." (PMID 34284787, 2021). "Recent studies show that Notch4 acts as an oncogene in some types of cancers, such as colorectal cancer, triple-negative breast cancer, and prostate cancer." (PMID 34988077, 2021). "Guiyang Wu and colleagues point out that the upregulation of Notch4 was significant in cancer tissues and liver metastases compared with adjacent normal tissues." (PMID 32211044, 2020).
cancer (continued). "For example, miRNAs such as MIR-181, MIR-30b, and MIR-200b as well as specific gene loci such as ADAMTS13, NOTCH4 and PIGN have been linked to many cancers, including EEC, and should be evaluated in vitro in the future." (PMID 30857319, 2019). "Similar results have been obtained by Farnie and colleagues who demonstrated that Notch4-neutralizing antibody inhibited cancer stem cell activity in vitro." (PMID 31379945, 2019). "Although Notch4 RNA expression in two cancer cell lines was slightly higher than the Het-1A cell line, the KYSE70 cell line expressed lower level of Notch4, and in general the Nocth4 expression in these four cell lines was low." (PMID 23409141, 2013). "Inspecting this list, we found several genes, such as thymidine phosphorylase (TYMP), apoptosis-related cysteine peptidase (CASP10), and notch 4 (NOTCH4), have been implicated in cancer cells, but most of the gene are novel ones." (PMID 24171174, 2013). "Collectively, these data point to an essential role for Notch4 in cancer recurrence through the maintenance of TICs." (PMID 23593654, 2013). "There was no significant change in the expression of Notch4 between normal and cancer tissues; however, the levels of Notch4 was the highest amongst all Notch receptors in normal tissue." (PMID 20030805, 2009). "Notch4 is considered a new biomarker of cancer stem cells (CSCs)." (PMID 38790158, 2024). "In some cancer cells, granules indicating the presence of Notch4 were visible within the nuclei." (PMID 37108670, 2023). "In addition to the Wnt/β-catenin signaling pathway, we demonstrated that KLF10 contributed to the cancer stemness phenotype by transcriptionally regulating Notch-3 and Notch-4 and competing with E74-like ETS transcription factor 3 (ELF3) for promoter binding." (PMID 37958386, 2023). "Moreover, increased Notch4 expression is known to facilitate drug resistance in different cancer types including CRC." (PMID 37751451, 2023). "In TNBC cells, Notch4 maintained cancer stemness and promoted metastasis, indicating that Notch4 could be a potential therapeutic target for TNBC treatment." (PMID 37149651, 2023). "We further examined whether the NOTCH4 mutations were preferentially associated with TMB and TNB, which are considered to be the common markers of pan-cancer immunotherapy." (PMID 35967450, 2022). "Then, NOTCH4 status and cancer type were subjected to multivariate Cox regression analysis of PFS." (PMID 34284787, 2021). "Indeed, Notch1 levels inversely correlated with the expression of E-cadherin in paclitaxel-resistant prostatic cancer, and GSI-mediated inactivation of Notch1 and Notch4 reversed the sensitivity of cancer cells to this taxane." (PMID 34680255, 2021). "Notch4 is involved in the migration and invasion of several kinds of cancers." (PMID 28725177, 2017). "The upregulation of Notch4 indicates that the Notch signaling pathway, important in breast development/cancer may be a potential target for novel RB therapies." (PMID 17615543, 2007). "Thus, anti-Notch4 treatment may have broad clinical benefits in different cancers at different stages." (PMID 38984877, 2024). "Hence it's impossible to generalize the role of Notch4 in progression of cancer." (PMID 29162408, 2019). "NOTCH3 and NOTCH4 regulate genes involved in BCAA catabolism, thereby affecting the TME and cancer cell metabolism." (PMID 39286249, 2024). "Thus, inhibiting Notch4 activity could be a promising and safe avenue for future cancer treatment." (PMID 38984877, 2024). "In HNSC, both expression and DEG enrichment of JAG1, DLL1, and NOTCH2 significantly increased after anti-cancer therapy, while DLL3 and NOTCH4 significantly decreased." (PMID 39074091, 2024). "Our results showed that silencing Notch4 upregulated Nanog expression and enhanced the tumorigenic ability of TNBC cells, consistent with previous findings of Nanog controlling cancer stem cell activity in TNBC cells." (PMID 37149651, 2023).
cancer (continued). "Of the 25 immune-related genes, 24 genes (96%) demonstrated higher expression levels in NOTCH4-Mut tumors compared with wildtype ones, but one gene (4%), EMP1, showed decreased expression, implying a potential decrease in cancer invasiveness and metastasis." (PMID 35967450, 2022). "In a pan-cancer (lung cancer, cervical cancer, prostate cancer, pancreatic cancer, colon cancer, kidney cancer, large cell and Hodgkin’s lymphoma, etc.)biomarker research published recently, NOTCH4 may serve as a potential predictive biomarker for ICI treatment." (PMID 35967450, 2022). "NOTCH1 and NOTCH4 play a key role in the EMT pathway to increase the migration and invasion of cancer cells to other body organs such as the lungs and especially the liver." (PMID 35928368, 2022). "Based on our data, activated forms of Notch1, Notch2, Notch3, and Notch4 (N1ICD, N2ICD, N3ICD, and N4ICD) in stomach-cancer cells were all upregulated, especially N1ICD and N2ICD, after the co-culture of cancer cells and macrophages." (PMID 35382168, 2022). "We expanded this observation to more cell lines by analyzing the RNA-seq data retrieved from Cancer Cell Line Encyclopedia (CCLE), demonstrating that SLUG and GAS1 were positively correlated with NOTCH4 in TNBC cell lines." (PMID 32104513, 2020). "Many factors, including EphA2, Notch4, VE‐cadherin, SLPI, TWIST, VEGF, vimentin and HIF‐1α, are related to the formation of VM in many cancers." (PMID 33118329, 2020). "NOTCH2 was slightly upregulated in three of the analyzed cancer cell lines as compared to control, while NOTCH3 and NOTCH4 were variable and low expressed in PTC cell lines TPC1 and BCPAP." (PMID 30158530, 2018). "Analysis revealed overexpression of APH1A, CTBP1, HEY1, HEY2, JAG2, NOTCH4 regardless of the cancer subtype." (PMID 41463075, 2025). "NOTCH2 and NOTCH4 are well-known genes in BRCA and other cancers." (PMID 38977697, 2024). "Multiple cancer survival-related genes were found in these genes, including CDH17, PTPRJ, SLC16A14, TMTC2, and NOTCH4." (PMID 32426342, 2020). "Assim, o presente estudo tem como objetivo determinar o padrão de expressão diferencial de Notch4 no carcinoma verrucoso e de células escamosas de cavidade oral." (PMID 29162408, 2019). "Our findings have potentially strong implications to understanding normal developmental processes that involve Notch4 function as well as cancer pathogenesis by providing a novel link between insulin and growth factor-activated AKT signaling and the transcriptional regulator Notch4." (PMID 25740432, 2015). "There was no detectable expression of NOTCH4 in these cancer cells by either western blot analysis or RT–PCR (data not shown)." (PMID 20010940, 2010). "Similar nuclear localization has been previously observed for Notch4 and epidermal growth factor receptor (EGFR) in cancers; however, their significance remains unknown currently." (PMID 20030805, 2009). "Unlike other Notch receptors, Notch4 exhibits distinct functions in different types of cancer, and blocking Notch4 activation could potentially affect the functioning of Notch1–3 receptors." (PMID 38203782, 2024). "While CAFs-S1 stimulate cancer cell migration and initiate an EMT through CXCL12 and TGFB pathways, highly contractile CAFs-S4 induce cancer cell invasion in 3 dimensions via NOTCH signaling (NOTCH1, bSE = 3.0; NOTCH2, bSE = 2.6; NOTCH3, bSE = 1.4; NOTCH4, SE = 3.0)." (PMID 39335478, 2024). "Esses achados preliminares apoiam fortemente o fato de que Notch4 estava regulado para baixo no carcinoma verrucoso oral e poderia ser considerado um marcador prognóstico adequado para distinguir entre carcinoma verrucoso e carcinoma de células escamosas de cavidade oral." (PMID 29162408, 2019). "Present data show that NILCO molecules (Notch1, Notch2, Notch3, Notch4, DLL4, and JAG1) and targets (Survivin, Hey2, IL-1R tI, and OB-R) were expressed in EmCa regardless of ethnicity and cancer type." (PMID 28659656, 2017).
cancer (continued). "We also examined the expression of other Notch receptors (Notch2, Notch3, and Notch4) in ICC tissue and noncancerous tissue adjacent to the cancer lesions." (PMID 23688168, 2013).
infection (9 papers, 2004 to 2025). The state of being infected such as from the introduction of a foreign agent such as serum, vaccine, antigenic substance or organism. "NOTCH4 is regarded as a regulator in inflammation which suppresses NF-κB in lung and infection models with potential parallels in gut immunity." (PMID 39769296, 2024). "An initial infection with the SARS-CoV2 virus resulted in the expansion of Notch4 and Notch1 Tregs, the latter favored by rare genetic variants found in the susceptible host." (PMID 36282598, 2023). "On the other hand, an excessive NOTCH4 activity could compromise the adequate defense of the organism against infections." (PMID 34925319, 2021). "Notably, the Notch4/DLL4 signaling pathway serves as a central regulator in the infection-mediated apoptosis, as evidenced by E. coli intrauterine infection models showing upregulated Notch4/DLL4 expression and enhanced pulmonary microvascular endothelial cell apoptosis." (PMID 41030317, 2025). "Moreover, NOTCH4 protein level was also induced by the infection with either H37Rv or BCG in PM." (PMID 36817473, 2023). "HEY1 levels were not reduced to baseline levels in the presence of NOTCH4 siRNA; this may be attributed to a receptor-independent induction of HEY1 as a consequence of the expression of low levels of KSHV ORF50 during primary infection, or due to incomplete knock-down of NOTCH4." (PMID 19816565, 2009).
adenocarcinoma (2 papers, 2009 to 2018). A common cancer characterized by the presence of malignant glandular cells. "Vasculogenesis-associated genes including NOTCH4 and TGFBR3 expression were significantly downregulated in adenocarcinoma tissue versus normal tissue (adjusted P values < 0.001 for both NOTCH4 and TGFBR3)." (PMID 29769567, 2018). "Notch 4 was −6.8-fold down regulated in adenocarcinoma compared to transgenic and −7.6-fold down regulated in the comparison adenocarcinoma versus non-transgenic." (PMID 19812696, 2009).
kidney (2 papers, 2022). "The METTL3-mediated m6A modification level of TIMP2 mRNA may promote podocyte injury, apoptosis in glomeruli, and kidney inflammation through upregulating the Notch3 and Notch 4 signaling pathways." (PMID 36157472, 2022).
immune disorders (1 paper, 2021). "However, recent work reported new functional roles for Notch3 and Notch4 in other cells relevant to immune disorders such as synovial fibroblasts and macrophages for Notch3, and regulatory T cells for Notch4." (PMID 34124039, 2021).
inflammation (1 paper, 2020). Aberrant reaction of the microcirculation characterized by movement of fluid and leukocytes from the blood into extravascular tissues. "It is noticeable that NOTCH4 expression is significantly reduced in patients with HLP, NOTCH4 is a pathogenic factor involved in the process that lipids lead to vascular endothelial inflammation." (PMID 33317561, 2020).
neurodegenerative disease (1 paper, 2024). A disorder of the central nervous system characterized by gradual and progressive loss of neural tissue and neurologic function. "More specifically, 1, 1, 312, and 4 mutations in Notch1, Notch2, Notch3, and Notch4, respectively, were identified to be correlated with neurodegenerative diseases." (PMID 38790158, 2024). "Finally, from the Notch4 gene were extracted only two SNPs (missense variants), and neither was found to be associated with neurodegenerative disease." (PMID 38790158, 2024).
NOTCH4 also shares sentences with these, for which no sentence is quoted: alopecia areata (3 papers); head and neck squamous cell carcinoma (3); stomach cancer (3); ulcerative colitis (3); allergic asthma (2); cardiovascular disease (2); celiac disease (2); cerebral small vessel disease (2); Crohn disease (2); essential hypertension (2); head and neck cancer (2); hemangioma (2); metabolic disease (2); multiple myeloma (2); myocardial infarction (2); pancreatic adenocarcinoma (2); papillary carcinoma (2); systemic lupus erythematosus (2); vasculitis (2); Adams-Oliver syndrome (1); adenoid cystic carcinoma (1); agranulocytosis (1); Anxiety (1); aortic stenosis (1); aortic valve disease (1); arteriosclerosis (1); astrocytoma (1); benign gynecologic tumors (1); brain disorder (1); cholangiocarcinoma (1).
A further 43 diseases each share a sentence with NOTCH4 in 1 paper.